STEAP1 (STEAP family member 1)
Diseases named in the same sentence as STEAP1 in open-access papers (continued):
Sharing a sentence is not in itself a finding about the gene and the disease.
tumor (continued). "Additional work will be necessary to understand the functional mechanisms underlying STEAP1 antigen loss and more generally how dynamic effects of adoptive CAR T cell therapy may contribute to antigen loss and immunoediting by modulating tumor-immune-stromal interactions in solid tumors." (PMID 37041154, 2023). "Several researchers exploring the role of STEAP1 in cancer have shown that its overexpression inhibits apoptosis, enhances cell proliferation, migration, and invasion, and induces epithelial to mesenchymal transition, ultimately contributing to tumor progression and aggressiveness." (PMID 37047621, 2023). "The remaining questions to answer include: STEAP1–4 expression patterns in different grades of PCa, the role of AR in regulating STEAP1–4 expression, other mechanisms by which STEAP1–4 promote PCa pathogenesis, and the roles of STEAP1–4 in the PCa tumor microenvironment." (PMID 36011027, 2022). "Bispecific T cell engagers (BiTEs), such as xaluritamig (AMG 509), simultaneously bind STEAP1 on cancer cells and CD3 on T cells, bridging them into close proximity, resulting in direct and potent activation of cytotoxic T cells to induce tumor cell killing." (PMID 40427518, 2025). "T-cell engagers (TCEs) offer a new frontier by directly linking T-cells to cancer cells via specific tumor antigens (like PSMA, STEAP1, and DLL3), bypassing traditional immune recognition." (PMID 40507301, 2025). "Mice were sacrificed on day 25 and residual tumors from mice treated with STEAP1-BBζ CAR T cells showed large areas of necrotic debris and regions of viable tumor were infiltrated with CD3+ STEAP1-BBζ CAR T cells." (PMID 37041154, 2023). "The different STEAP1 CAR T cells (JK59, Dnm, and JK11), as well as control T cells (CD19 CAR, NT) were co-cultured with STEAP1+/− tumor cells at different effector-to-target (E:T) ratios." (PMID 36830995, 2023). "However, this sensitivity of STEAP1-BBζ CAR T cells to low levels of STEAP1 expression may be advantageous from the perspective of enhancing antitumor efficacy but could also accentuate liabilities from on-target off-tumor toxicity." (PMID 37041154, 2023). "The STEAP1 CAR T cells showed a strong and statistically significant anti-tumor efficacy, compared with the control CD19 CAR T cells." (PMID 35860008, 2022). "Investigation to TME in multiple cancers revealed that STEAP1 was positively correlated with the major of immune infiltration, especially in BRCA, COAD, KIRP, PAAD, and THCA but negatively correlated with tumor-immune infiltration in PRAD, THYM, and UVM." (PMID 35313641, 2022). "Transfection of the STEAP1 3' UTR reporter into HMrSV5 cells (normal) and MKN45 cells (tumor) revealed a significant increase in reporter activity specific in the MKN45 cells." (PMID 31949502, 2020). "We have previously demonstrated that blockade of PD-1 receptor in combination with STEAP1 heterologous vaccination enhances efficacy and significantly improves survival of mice in the TRAMP-C1 subcutaneous tumour model." (PMID 28537896, 2017). "For STEAP1 ADC tumor uptake, highest values (38.7 ± 1.5 %ID/g) were measured in LuCaP35V tumors, lowest tumor uptake in LuCaP96.1 tumors (4.7 ± 0.3 %ID/g)." (PMID 27029064, 2016). "The quantification of Ki-67 positive staining shows higher values in the control group as compared to STEAP1-vaccinated mice, which in turn demonstrated a slight increase in CD3+ tumour-infiltrating lymphocytes as compared to control mice." (PMID 27052571, 2016). "The third class of isolated yeast cell death suppressors includes molecules such as PAICS, STEAP1 and MALAT1, for which overexpression and/or functional relevance in tumor biology has been published." (PMID 23717670, 2013).
tumor (continued). "Synthesizing the early clinical data presented for TCEs targeting PSMA, STEAP1, and DLL3, a compelling picture emerges: T-cell engagers possess the intrinsic capability to elicit meaningful anti-tumor activity in heavily pretreated mCRPC patients, a population often refractory to standard therapies." (PMID 40507301, 2025). "Of note, the AR+ HOXB13–negative GRN in the ARhigh/PSMAlow sample showed robust STEAP1 and STEAP2 expression, suggesting that co–targeting of STEAP and PSMA in AR–positive disease may be an effective strategy to achieve broader tumor cell coverage." (PMID 38645034, 2024). "Meanwhile, the gene STEAP1 was found to have an average of five-fold increase in tumor tissue compared to non-tumor tissue in the 9 cases (not shown)." (PMID 38830975, 2024). "These include dual antigen-targeted (e.g., PSMA and STEAP1) CAR T cell therapies or multimodal strategies combining CAR T cell therapies with ADCs, T-BsAbs, or other treatments that potently promote antigen-independent and -dependent tumor killing." (PMID 37041154, 2023). "The STEAP1 CAR T cells did, however, retain a substantial level of anti-tumor activity." (PMID 36830995, 2023). "A mixed Th1/Th2 profile is in line with observations we have previously made for T cells transduced with tumor-targeting TCRs or the JK11 STEAP1 CAR and in studies of cancer vaccine responses, where a strict Th1/Th2 dichotomy did not apply even in monoclonal T cell cultures." (PMID 36830995, 2023). "Non-tumor bearing mice treated with untransduced T cells or STEAP1-mBBζ CAR T cells did not demonstrate any differences in survival or gross toxicities including loss of body weight." (PMID 37041154, 2023). "Following the co-expression and network analyses, this signature was found to be enriched for genes involved in the regulation of the stroma component of the tumor (TDO2, STEAP1) as well as Treg cells (SLC16A1, PRKAB1) and myeloid cell (APOBEC3A, MERTK, SNX29) subsets." (PMID 36216827, 2022). "The results showed that STEAP1 and STEAP2 expression was correlated with tumor stage." (PMID 35346237, 2022). "We observed T cell infiltration into the tumor only in mice injected with wild-type 22Rv1 and treated with STEAP1 CAR T cells, not in the other three mouse groups." (PMID 35860008, 2022). "Assessment of 535 specimens of LUAD tissue and 59 tumor-adjacent normal tissue specimens in TCGA database revealed that STEAP1 was significantly upregulated in LUAD tissues rather than in the adjacent non-cancerous tissues (P < 0.05)." (PMID 32265985, 2020). "Some previous research on different kinds of cancer have found that STEAP1 was observed in tumour tissue but not in normal tissue." (PMID 33128353, 2020). "In contrast, tumor uptakes of 111In-ADC at 72 h were predose dependent at 27 ± 6, 28 ± 3, 24 ± 4, and 16 ± 2 with 0, 0.5, 1, and 3 mg/kg anti-TENB2 predoses, respectively, and 35 ± 6%ID/g with a 3 mg/kg anti-STEAP1 predose." (PMID 31692898, 2019). "Tumor uptakes of 125I-ADC at 72 h were relatively flat at 3.4 ± 0.8, 3.7 ± 0.5, 3.6 ± 0.4, and 2.9 ± 0.5 with 0, 0.5, 1, and 3 mg/kg anti-TENB2 predoses, respectively, and 3.8 ± 1.0%ID/g with a 3 mg/kg anti-STEAP1 predose." (PMID 31692898, 2019). "The STEAP1 mRNA transcript was not amplified from total thymic RNA, while a shared tumour antigen, 5T4, and β-actin were both amplified by RT-PCR." (PMID 27052571, 2016). "Tumor tracer uptake of 111In labeled TENB2, STEAP1 and gD mAbs showed varying results." (PMID 27029064, 2016). "These staining results fit with the biological properties and with the previously reported results from studies on different types of cancer, where STEAP1 was detected in the tumor portion but not in adjacent parts of the specimens." (PMID 27104516, 2016). "In this article, we have shown that STEAP1 ChAdOx1–MVA vaccination platform delays growth of pre-established ectopic tumours at the early stages of tumour growth and modestly controls autochthonous tumours in TRAMP mice." (PMID 27052571, 2016).
tumor (continued). "We hypothesised that exposure to a lower amount of antigen could favour activation of high-avidity STEAP1-specific T-cells, which would be more efficient in targeting weakly immunogenic TRAMP-derived tumours." (PMID 27052571, 2016). "Crucially, objective tumor responses (ORR according to RECIST) have also been documented, with rates spanning from approximately 10% in some initial PSMA trials to encouraging figures exceeding 40% in higher-dose cohorts of the STEAP1-targeting Xaluritamig study." (PMID 40507301, 2025). "In a disseminated, syngeneic RM9-hSTEAP1 tumor model in hSTEAP1-KI mice, STEAP1 CAR T cells combined with a collagen binding domain IL-12 enhanced OS, cytokine production, tumor antigen presentation, and dissemination with epitopes to prevent STEAP1 antigen escape." (PMID 38693513, 2024). "These exciting therapeutic developments in targeting PSMA, KLK2, STEAP1, and PSCA in mCRPC have opened tremendous opportunities for sequencing treatment targeting the same tumor surface antigens with different strategies or different tumor surface antigens with the same or different strategies." (PMID 39272956, 2024). "One of the STEAP1 CAR mice had no detectable tumor at study termination." (PMID 35860008, 2022). "First, STEAP1 overexpression in PCa may be the result of its local tumor microenvironment (rather than solely due to STEAP1 overexpression in primary tumor cells)." (PMID 36011027, 2022). "Therefore, establishing tumor uptake and TENB2 or STEAP1 presence may well have value in choosing appropriate treatments in the future." (PMID 27029064, 2016). "However, these alterations do not justify the overexpression of STEAP1 in tumor cells, suggesting that other mechanisms may be involved." (PMID 34833128, 2021). "Overall, our results show that ectopic tumour growth can be delayed and disease progression can be inhibited in mice by STEAP1-specific T-cell responses, although tumour development could not be completely prevented despite the strong immunogenicity of the vaccine." (PMID 27052571, 2016). "Other prostate cell surface antigens, such as prostate stem cell antigen (PSCA) and six-transmembrane epithelial antigen of the prostate 1 (STEAP1), also exhibit nonspecific expression profiles, potentially leading to similar on-target, off-tumor effects." (PMID 40627156, 2025). "Off-tumor toxicity is addressed primarily by selecting prostate-specific antigens, such as PSMA and STEAP1, to minimize risks to non-prostate tissues." (PMID 40507301, 2025). "In conclusion, we suggest that STEAP1, 2, 4 and DMT1 are suitable candidates to distinguish patients with cancer from those that have no tumour present." (PMID 31393902, 2019). "Thus, it is likely that TRAMP tumours are not recognised by vaccination-induced low-avidity T-cells because of their low MHCI and STEAP1 endogenous expressions." (PMID 27052571, 2016). "Tumor uptake was higher in mice administered 89Zr–anti-TENB2 or 89Zr–anti-STEAP1 compared to mice given the control mAb 89Zr–anti-gD (p < 0.05); the exception was 89Zr-anti-STEAP1 uptake in LuCaP96.1 tumors which was no higher than control." (PMID 27029064, 2016).
cancer (67 papers, 2011 to 2026). A tumor composed of atypical neoplastic, often pleomorphic cells that invade other tissues. "STEAP1 is a membrane-bound channel protein found overexpressed in various cancers and was associated with a malignant phenotype and disease prognosis." (PMID 37999477, 2023). "STEAP1 expression has been linked to increased cell proliferation, tumorigenicity, metastasis, and invasiveness in various cancers." (PMID 34073779, 2021). "Ultimately, understanding the molecular principles that underly the function of STEAP1 will guide the design of anti-STEAP1-focused cancer therapies, thereby exploiting the protein's high expression in cancer and minimal presence in healthy cells." (PMID 32409586, 2020). "Six transmembrane epithelial antigen of the prostate 1 (STEAP1) is a tumor-associated antigen due to its high expression in several cancers, including EwS." (PMID 32610710, 2020). "Previous studies have suggested an association between STEAP1 and the malignant phenotype of cancer cells." (PMID 27104516, 2016). "Further analysis showed that STEAP1 had a more significant association with clinical outcome in elderly patients and in patients with late stage cancers, late T values, and early N values." (PMID 27104516, 2016). "Accordingly, multivariate analysis identified low STEAP1 expression as an independent risk factor (hazard ratio = 1.500, p = 0.018), especially in elderly patients or those with late stage cancers, late T values, and early N values." (PMID 27104516, 2016). "On the other hand, SPP1, SPINK1 and STEAP1 are proteins that are up-regulated in several human carcinomas and their overexpression is also associated to cancer progression." (PMID 24865347, 2014). "Differential gene expression analysis showed overexpression of classic epithelial genes (for example, SFTPC and STEAP1), genes associated with cancer (for example, CLDN6) and regulators of EMT (for example, VIM, FN 1 and CDH2) in Oncopig LC versus normal pig lung tissues." (PMID 41407936, 2026). "Differential gene expression analysis showed overexpression of classic epithelial genes (e.g., SFTPC and STEAP1), genes associated with cancer (e.g., CLDN6), and regulators of EMT (e.g., vimentin, fibronectin 1, and N-cadherin) in Oncopig LC versus normal pig lung tissues." (PMID 39975891, 2025). "Increased STEAP1 expressions were associated with high grade of BLCA, HNSC, LGG, and STAD while high grade of KIRC and UCEC was associated with lower STEAP1 expression levels, suggested STEAP1 could be considered an underlying biomarker in certain cancers." (PMID 35313641, 2022). "STEAP1 is aberrantly expressed in multiple tumors and is associated with the occurrence, development, and prognosis of malignant tumors, indicating that STEAP1 might be a potential diagnostic and therapeutic marker for cancers." (PMID 32265985, 2020). "However, STEAP1 is highly overexpressed in PCa along with 10 other cancers including brain, lung and pancreatic and is associated with poor prognosis and shorter biochemical recurrence survival." (PMID 31393902, 2019). "Although STEAP1 has been considered as an optimal target for T cell-based immunotherapy, with applications in a subset of cancer types nowadays, its expression and mutation landscape as well as prognostic value in many other cancers still remained to be investigated." (PMID 35313641, 2022). "STEAP1 is overexpressed in several types of human cancer tissues and cell lines, including prostate, bladder, colon, pancreas, ovary, testis, breast, cervix, and Ewing sarcoma and has been implicated as a driver of cancer cell proliferation, invasion, and immune evasion." (PMID 32328462, 2020). "Clinical studies have demonstrated that bsAbs targeting STEAP1 can be effective treatments for advanced PCa, with xaluritamig producing significant radiographic and PSA responses, confirming STEAP1 as a viable cancer target." (PMID 41153826, 2025).
cancer (continued). "These approaches aim to harness the immune system and targeted drug delivery to specifically attack STEAP1-expressing cancer cells, potentially overcoming resistance in CRPC." (PMID 41235005, 2025). "STEAP1, a PCa membrane protein, not only demonstrates potential as a sensitive biomarker for cancer detection through plasma EVs or molecular imaging examinations but also demonstrates promising therapeutic utility via direct or indirect targeting." (PMID 40299363, 2025). "Although STEAP1 is overexpressed in multiple cancers, its expression is exceptionally high in PCa, combined with its functional linkage to disease progression, making it an optimal target for detection and treatment." (PMID 40299363, 2025). "Recent studies showed that this STEAP1 CAR exhibits potent anti-cancer activity in vitro and in animal models." (PMID 40270044, 2025). "We have developed a CAR where the scFv recognizes the protein six-transmembrane epithelial antigen of prostate-1 (STEAP1), a protein expressed in multiple cancer forms." (PMID 38203757, 2024). "In this review, we initially focus on the molecular mechanisms and functions of STEAP1 by cancer type and subsequently present several potential therapeutic strategies targeting STEAP1 based on previous pre-clinical and clinical reports." (PMID 37909017, 2023). "STEAP1 has been appointed as a putative biomarker and therapeutic agent in a plenitude of cancers, with higher expression levels in PCa." (PMID 36768273, 2023). "Cancer vaccines for STEAP1 have been developed because several epitopes of STEAP1 are recognized by cytotoxic T lymphocytes (CTLs) and successfully evoke the activation of CTLs." (PMID 37909017, 2023). "Collectively, it is assumed that multiple pathways exist between STEAP1 and ROS in a cancer-type specific manner." (PMID 37909017, 2023). "The results of bioinformatic analysis indicated that c-Myc, which is known to contribute to the pathogenesis of a broad range of human cancers, lies downstream of STEAP1, and the pathway promotes cell proliferation and cell-cycle progression in HCC." (PMID 37909017, 2023). "STEAP1 is rapidly gaining attention as a novel therapeutic target because of its location on the cell surface and specificity to cancer versus normal cells." (PMID 37909017, 2023). "As discussed in section 3, STEAP1 is an ideal target of cancer treatment because it is located on the cell surface and is specifically expressed in various types of cancer." (PMID 37909017, 2023). "STEAP1 has an established functional role in promoting cancer cell proliferation, invasion, and epithelial-to-mesenchymal transition." (PMID 37041154, 2023). "In this section, we discuss the molecular mechanisms and functions of STEAP1 in a cancer-type-dependent manner." (PMID 37909017, 2023). "Six-transmembrane epithelial antigen of prostate 1 (STEAP1) is a membrane protein overexpressed in cancer cells." (PMID 37489365, 2023). "Given the widespread expression of STEAP1 in late-stage mCRPC and its reported functional role in cancer progression, we next started to engineer a lentiviral STEAP1-specific second-generation CAR." (PMID 37041154, 2023). "The T cells acquired the desired anti-STEAP1 specificity, with a polyfunctional response including production of multiple cytokines, proliferation, and the killing of cancer cells." (PMID 35860008, 2022). "Nonetheless, there were few systematic studies of STEAP1 in pan-cancer by bioinformatics approaches." (PMID 35313641, 2022). "These preliminary findings suggested that STEAP1 acted as an important role in chemosensitivity or resistance in cancer cells and served as a potential target to constrain drug resistance in different cancers." (PMID 35313641, 2022). "This study is aimed at systematically analyzing the expression, function, and prognostic value of STEAP1 in various cancers." (PMID 35313641, 2022).